TNF (tumor necrosis factor)
Diseases named in the same sentence as TNF in open-access papers (continued):
Sharing a sentence is not in itself a finding about the gene and the disease.
vitiligo (continued). "TNF-α has a key role in the pathogenesis of vitiligo as it affects the apoptosis of melanocytes." (PMID 33370782, 2020). "Differences in TNF-α serum level (pg/ml) in relation to clinical data in vitiligo patients." (PMID 33370782, 2020). "Nonetheless, TNF-α inhibitors can be useful to halt disease progression in active vitiligo." (PMID 31440261, 2019). "Furthermore, inflammatory factors and interleukin (IL) signaling pathway (IL4 and IL10), adaptive immune response (IFNG), and cell apoptosis (FASLG and TNF) also played critical roles in the clarification of the mechanisms of KBL on vitiligo." (PMID 31781265, 2019). "However, the apparent efficacy of TNF-α inhibitors in toxic epidermal necrolysis and occasional cases of alopecia areata and vitiligo suggest that the role of TNF-α is more complex." (PMID 31440261, 2019). "Additionally, imiquimod binds to Toll-like receptor-7 and −8, increasing production of proinflammatory cytokines such as IFN-α, TNF-α, and LI-12, which play a role in the pathogenesis of vitiligo." (PMID 24928346, 2014). "The authors hypothesized that TNF-alpha inhibits melanocyte stem cells differentiation; thus TNF-alpha inhibitors may serve as an effective therapy for vitiligo." (PMID 24665368, 2014). "More detailed studies regarding the role of TNFB in precipitation of vitiligo and the development of effective anti-TNF agents may prove to be useful as preventive/ameliorative therapies." (PMID 24312346, 2013). "TNF-α also affects the apoptotic pathway of melanocytes and its level may play an important role in vitiligo pathogenesis." (PMID 23284977, 2012). "In whitish patches of vitiligo, the expression of TNF-α is high." (PMID 22778983, 2012). "More detailed studies regarding role of TNF-α in precipitation of vitiligo and the development of effective anti-TNF-α agents may prove to be useful as preventive/ameliorative therapies." (PMID 23284977, 2012). "In vitiligo affected skin, a significantly higher expression of TNF-α, IL-6, IFN-γ was detected compared with healthy controls and perilesional, non-lesional skin indicating that cytokine imbalance plays an important role in the depigmentation process of vitiligo." (PMID 23284977, 2012). "In addition, we analyzed the TNF-α expression based on the progression of the disease i.e. active vitiligo and stable vitiligo." (PMID 23284977, 2012). "Our results clearly suggest the important role of TNF-α in pathogenesis of vitiligo." (PMID 23284977, 2012). "In conclusion, our findings suggest that the increased TNF-α levels in vitiligo patients could result, at least in part, from variations at the genetic level." (PMID 23284977, 2012). "Also, increased TNF-α levels have been observed in skin samples from patients with vitiligo." (PMID 40861456, 2025). "Calcineurin inhibitors are immunomodulators and an off-label treatment for vitiligo functioning via inhibiting the lymphocyte and dendiric cells resident proinflammatory protein (calcineurin) that is responsible for the transcription of interleukin (IL)-2 and tumor necrosis factor-α (TNF-α)." (PMID 38850408, 2024). "In addition, a cohort study involving 11,442 patients found anti-TNF agents to significantly increase the risk of vitiligo but not alopecia areata." (PMID 39201060, 2024). "Indeed TNF-α is increased within vitiligo lesions when compared to normally pigmented skin." (PMID 37275386, 2023). "In addition, NK cells receptors, including natural killer cell triggering receptor (NKTR), killer cell lectin-like receptor C1 (KLRC1), CCL20, and NK cell-related cytokines such as TNFα and IL-15, are also increased in perilesional skin in patients with vitiligo." (PMID 35884944, 2022). "In vitiligo, IL-33 may be considered an alarmin; it may be released by apoptotic or necrotic keratinocytes and inhibits melanocytes growth, blocking growth factors and increasing pro-inflammatory IL-6 and TNFα expression." (PMID 34768860, 2021).
vitiligo (continued). "However, this does not agree with previous reports demonstrating that TNF-α-308 SNP did not confer risk or vitiligo susceptibility." (PMID 33370782, 2020). "Thus in this case report, the role of TNF-alpha seems probable in vitiligo." (PMID 24665368, 2014). "Several candidate genes have been linked to vitiligo, such as genes involved in the leukocyte antigen system (HLA, MIM 615161), cytotoxic T lymphocyte-associated 4 (CTLA4, MIM 123890), tumor necrosis factors (TNFα, MIM 191160), and autoimmune regulators (AIRE gene, MIM 607358)." (PMID 25548428, 2014). "Moreover, vitiligo patients show higher lesion levels of TNF-α." (PMID 23284977, 2012). "In vitiligo, CD4+ and CD8+ T cells play crucial roles by producing Th1/Tc1 signature cytokines such as IFN-γ and TNF-α." (PMID 40861456, 2025). "Pioneering investigations have demonstrated that subgroup cells infiltrating the perilesional skin of vitiligo exhibit a Th1-skewed phenotype, which leads to an enhanced production of inflammatory cytokines like IFN-γ and TNF-α." (PMID 40725033, 2025). "Several inflammatory and immune‐related pathways showed significant upregulation in vitiligo, including IL1, IL6, TNF, MHC‐I, MHC‐II, and various cytokine signaling cascades." (PMID 41498037, 2025). "In addition, a variety of cytokines secreted by T helper cell subsets- Th1 (IFN-γ, TNF-α, IL-2) and Th2 (IL-4, IL-10, IL-13) not only exacerbate autoimmune responses but also perpetuate the vicious cycle of immune dysfunction, ultimately leading to the clinical manifestations of vitiligo." (PMID 40725033, 2025). "Compared with pretreatment psoriatic lesions, posttreatment vitiligo lesions displayed higher staining levels of CD8, IFN-γ, and CXCL10, whereas staining levels of IL-17A and TNF-α were lower." (PMID 40861456, 2025). "Concurrently, the cytokine profile shift—characterized by reduced IFN-γ, TNF-α, and IL-2, alongside elevated IL-4 and IL-10—suggests that LEF promotes an anti-inflammatory milieu, countering the Th1 axis that drives vitiligo." (PMID 40725033, 2025). "Consistent with this, previous reports have documented cases of vitiligo induced by biologic drugs such as anti-IL17 agents and anti-TNF α drugs." (PMID 39742272, 2024). "Interestingly, through MR analysis, we identified TNFRSF11B, TNF alpha induced protein 3 (TNFAIP3), TNF superfamily member 12 (TNFSF12) as potentially protective factors against vitiligo, which may explain why some patients experience depigmentation after using TNF inhibitors." (PMID 38660673, 2024). "The findings showed that patients with active vitiligo had increased levels of ROS, high levels of MDA, AND IL‐6, TNF‐a, IL‐1b, IFN, and IL‐8." (PMID 39313936, 2024). "Furthermore, vitiligo is defined by the presence of an altered immunological balance, which is predominantly seen in an imbalance between the cytokines expressed by Treg/Th2 lymphocyte subsets (IL-4) and Th1/Th17 lymphocyte subsets (TNF-α, IFN-γ, IL-17, and IL-8)." (PMID 38695020, 2024). "In active disease the levels of MMPs, especially MMP-9, are elevated in the lesional skin of vitiligo patients under the influence of IFN-γ and TNF-α." (PMID 37275386, 2023). "In the present study, we observed increased levels of IL-8, IL-6, TNF-α, IFN-γ and IL-1β in the skin of monobenzone-induced vitiligo mice, and LBP significantly inhibited secretion of IL-8, IL-6, TNF-α, IFN-γ and IL-1β." (PMID 36655287, 2023). "A relevant study demonstrated that NKG2D is upregulated in vitiligo skin and produces elevated levels of both IFN-γ and TNF-α." (PMID 38293673, 2023). "T cell memory cells penetrate the epidermis and convey vitiligo maintenance by generating IFN γ and TNF α, therefore resulting in a cytotoxic action against melanocytes." (PMID 37762802, 2023).
vitiligo (continued). "Matrix metalloproteinase (MMP)-9, an enzyme engaged in remodeling of the extracellular matrix (ECM), plays a vital role in response to interferon (IFN)-γ and tumor necrosis factor (TNF)-α, cytokines that are characteristic of vitiligo." (PMID 36980277, 2023). "Taken together, these findings suggest the involvement of the TNF-α/TNFR pathway and IFN-γ pathway in melanocyte apoptosis of vitiligo." (PMID 36980277, 2023). "Multiple monoclonal antibodies are available for vitiligo treatment, targeting IFN-γ, CXCL10, CXCR3, HSP70i, IL-15, IL-17/23, and TNF." (PMID 36119071, 2022). "The main cytokine networks explored in the pathogenesis of vitiligo are IFN-γ and TNF-α, in addition to IL-15 and Th17-related cytokines such as IL-17 and IL-23." (PMID 35884944, 2022). "The TRM from skin of vitiligo patients with active disease displayed increased IFN-γ and TNF-α production compared to stable disease and healthy controls, suggesting that TRM in vitiligo are poised for production of these cytokines." (PMID 33669367, 2021). "In particular, a subset of tissue-resident memory CD8 T (TRM) cells populating lesion areas in the skin of vitiligo patients was shown to have increased NKG2D levels and to be responsible for the increased production of IFN-γ and TNF-α." (PMID 33717132, 2021). "In dogs, we found enrichment of T cell gene signatures, with upregulation of IFNG, TNF, PRF1, IL15, CTSW, CXCL10, and CCL5 in both VKH and vitiligo in dogs compared to healthy controls." (PMID 33384688, 2020). "Several cytokines and chemokines contribute to the development of vitiligo and VKH, including type 1 responses (IFNγ, CXCL9/10/11, IL-12, TNF) type 17 responses (IL-17, CCL20, IL-23) and IL-2, which supports T cell growth and survival." (PMID 33384688, 2020). "The vitiligo case exhibited even higher ISG15 and PRF1, while IFNG, TNF, IL12, and IL15 levels were closer to those in healthy controls." (PMID 33384688, 2020). "An increase in tumor necrosis factor alpha (TNF-α), interferon-gamma (IFN-γ), and interleukin- (IL-) 1 compared to healthy skin suggests that vitiligo is mediated by cytotoxic T cells and T helper cell-1 (Th1) response." (PMID 28828385, 2017). "We also investigated AHR-related cytokines and observed increased serum TNF-α concentration and diminished serum levels of IL-10 and TGF-β1 in vitiligo." (PMID 26370050, 2015). "Some studies revealed that TNF-α can decrease ZAG expression and secretion; hence, increased expression of this cytokine in the site of vitiligo can result in a decrease of ZAG expression." (PMID 22778983, 2012). "T cells expanded from peri-lesional vitiligo skin show apredominately type 1 cytokine profile (i.e. IFN-γ and TNF-α)." (PMID 21541348, 2011). "The illness Th1(TNF-α, IFN-γ) is traditionally assumed to predominate in vitiligo." (PMID 38695020, 2024). "Activation of apoptosis triggered by the Fas/Fas ligand interaction can be mediated by molecules which are involved in the pathology of vitiligo including CD8+ T cells, the TNF-α/TNR receptor (TNFR) pathway, the IFN-γ signaling pathway, and the CXCL10/CXCR3B pathway." (PMID 36980277, 2023). "ICAM-1, a glycoprotein which enhances T-cell melanocyte attachment probably induced by TNF-α and IFN-γ, showed higher expression in vitiligo patients, which could represent links between cytokines and T-cell involvement in the pathogenesis of vitiligo." (PMID 36980277, 2023). "The IHC-positive areas of IL-6 and TNF-α of the FHB high-dose treatment group (HQ+7.2g/kg FHB) were even lower than those of the control group, indicating that FHB strongly inhibited inflammation in the topical vitiligo skin." (PMID 37575231, 2023). "Moreover, there is an increase in proinflammatory cytokines, characteristic of innate immunity, in both serum and skin of patients with vitiligo, such as IL1α, IL1β, IL6, IL8, IL12, IL15, and TNFα." (PMID 35643735, 2022).
vitiligo (continued). "Research is in progress to investigate the important cytokines involved in the pathogenesis of vitiligo, including IFN-γ, CXCL10, CXCR3, HSP70i, IL-15, IL-17/23, and TNF, the blockade of which has undergone preliminary attempts in animal models and some patients." (PMID 36119071, 2022). "At the age of 12 years, while still on MTX and anti-TNF therapy he had onset of new symptoms that included alopecia areata, vitiligo, and diarrhea without blood or mucus.." (PMID 36503523, 2022). "INFγ is strictly involved in the development of the disease but TNF-α does not seem to have the same role, as demonstrated in TNFα-knockout mice, which are not protected by the development of vitiligo." (PMID 34768860, 2021). "Also, it is characterized by the fact that it allows the activation of immune cells and the production of proinflammatory cytokines such as TNF‐α, IL‐1β, and IFN‐γ, which have proposed to play an essential role in the pathogenesis of vitiligo." (PMID 32705792, 2020). "Interestingly, they also observed significantly decreased levels of IL-6, TNF-α, IFN-γ, and IL-13 in sera of vitiligo mice models." (PMID 33613564, 2020). "The macrophage migration inhibiting factor (MIF) is a protein that promotes the activation of immune cells and the production of other proinflammatory cytokines such as TNF‐α, IL‐1β, and IFN‐γ, which have proposed to play an essential role in the pathogenesis of vitiligo." (PMID 32705792, 2020). "It has already been reported that both TNF-α and IL-1α are increased in non-segmental vitiligo lesions." (PMID 31505868, 2019). "Another hypothesis is that HLA-G expressed on the skin of vitiligo patients interacts with KIR2DL4 receptors from NK cells, and this interaction may induce the production of proinflammatory cytokines such as IFN-γ, TNF-α, IL-1α, IL-1β, IL-6, and IL-8." (PMID 31505868, 2019). "Studies have shown that various cytokines including interferon-γ (IFN-γ), tumor necrosis factor α (TNFα) and chemokine (C-C motif) ligand 22 (CCL22) are differentially expressed in the lesional skin and serum of vitiligo patients and health controls, indicating their roles in vitiligo." (PMID 24681574, 2014). "It is sensible to do larger studies on TNF-alpha inhibiting agents since there is no definite cure or safe therapy for vitiligo patients so far." (PMID 24665368, 2014). "There are increased levels of TNF-alpha and interleukin-1 (IL-1) in vitiligo lesions compared to normal skin." (PMID 24665368, 2014). "Intriguingly, repeated stimulations of fibroblasts with tumor necrosis factor-alpha (TNF-α) or IL-α, two pro-inflammatory cytokines that are higher expressed in lesional skin of vitiligo patients, stimulate the appearance of biomarkers of in vitro aging in a stress-dependent manner." (PMID 23555779, 2013). "EGCG significantly attenuated histopathologic changes (vitiligo) in the skin by reducing excessive inflammatory responses, especially the infiltration of CD8+ T cells, and by markedly inhibiting inflammatory mediators such as tumor necrosis factor‐alpha (TNF‐α) and IL‐6 levels." (PMID 41243839, 2025). "The potential mechanism of imiquimod-induced vitiligo involves interaction with Toll-like receptor 7 (TLR7) present on skin cells, which stimulates the production of various cytokines, including interferon (IFN)-α, tumor necrosis factor alpha (TNF-α), interleukin (IL)-6, IL-1, IL-8, and IL-12." (PMID 40920788, 2025). "Type 1 cytokines IFN-γ and TNF-α induce melanocyte detachment via E-cadherin disruption and the release of its soluble form, possibly due to increased matrix metalloproteinase 9 (MMP9) in the skin and blood in vitiligo patients, contributing to vitiligo pathogenesis." (PMID 38673994, 2024). "Indeed, TNF-α levels in vitiligo lesions are higher than those in non-lesional skin and are closely related to disease activity." (PMID 37175894, 2023).
vitiligo (continued). "Consequently, it can be concluded that anti-TNF-α agents have not proven effective in the treatment of vitiligo, based on current evidence." (PMID 38139134, 2023). "However, IL-33 is also speculated to have a positive feedback loop with tumor necrosis factor alpha (TNF-α), which induces melanocyte death resulting in vitiligo." (PMID 36817442, 2023). "In this context a relevant pathologic role in vitiligo was conferred to a subset of tissue-resident memory CD8+ T cells in lesion areas in the skin of vitiligo patients; these cells moreover present enhanced NKG2D levels and produce increased levels of IFN-γ and TNF-α cytokines." (PMID 36902117, 2023). "However, a recent study found decreased levels of IFN-α in the circulation of patients with vitiligo, and increased levels of circulating DCs, IL-12, and TNF-α in patients with non-segmental vitiligo." (PMID 35884944, 2022). "Pro-inflammatory cytokines such as tumor necrosis factor alpha (TNF-α), interleukin-6 (IL-6), interleukin-8 (IL-8), interleukin-1β (IL-1β), IFN-γ, and some anti-inflammatory cytokines such as interleukin-5 (IL-5) and IL-10 are increased in patients with active vitiligo." (PMID 36439174, 2022). "KEGG results showed that MDEGs were significantly enriched in IL-17 signaling pathway, Th17 cell differentiation, TNF signaling pathway, and NOD-like receptor signaling pathways, and these signaling pathways have been proved to be involved in mediating the immune regulation of vitiligo." (PMID 33790887, 2021). "It is suggested that topical agent that may reduce TNF-alpha in the epidermis (like tetracycline) is evaluated further in the treatment of vitiligo, since it is safe and not as expensive as TNF-alpha blocking agents." (PMID 24665368, 2014). "Thus, to verify if Ins and IGF-1 evoke a pro-inflammatory feature in vitiligo keratinocytes and the possible role in immunopathogenesis, we quantified the amount of several secreted interleukins that demonstrated increased quantities of CXCL10, IL-6, IL-8, IL-1α, IL1-β, and TNFα." (PMID 40277891, 2025). "In vitiligo mice, IFN-γ, TNF-α, and IL-2 levels were significantly elevated compared to normal controls (p < 0.001 for all cytokines)." (PMID 40725033, 2025). "TNF-α and NKT cells are involved in the pathogenesis of non-segmental vitiligo (NSV) whereas TNF-α inhibitors have been reported to successfully treat cases of vitiligo." (PMID 36187493, 2022). "Although it would be reasonable to propose TNF-α inhibitors for the treatment of vitiligo, the results of TNF-α inhibitors for treatment of vitiligo are not promising and even resulted in worsening of vitiligo." (PMID 35884944, 2022). "Like multiple previous studies we could only detect very moderate upregulation of some inflammatory cytokines such as TNF (p < 0.05) and IL36A (alias IL1F6) (p < 0.05) in vitiligo lesional or non-lesional skin." (PMID 30515176, 2018). "Meanwhile, there is mounting evidence that the immunological milieu of vitiligo is also characterized by cytokines connected to other Th2 cell responses, such as IL-4, IL-5, IL-10, IL-13, and IL-31, rather than just Th1 cells and related cytokines (IFN-γ, TNF-α, and IL-2)." (PMID 38695020, 2024).